DNMT3A (DNA methyltransferase 3 alpha)
Diseases named in the same sentence as DNMT3A in open-access papers (continued):
Sharing a sentence is not in itself a finding about the gene and the disease.
ischemia (3 papers, 2013 to 2019). A hypoperfusion of the BLOOD through an organ or tissue caused by a PATHOLOGIC CONSTRICTION or obstruction of its BLOOD VESSELS, or an absence of BLOOD CIRCULATION. "Increases in Dnmt3a mRNA levels were only observed in the CA3 region at 6 h after ischemia." (PMID 26496940, 2015). "Following ischemia, down-regulation of miR-29c might derepress DNMT3a translation resulting in increased amounts of DNMT3a protein as observed in the present study." (PMID 23516428, 2013). "Both DNMT1, which functions in DNA methylation maintenance, and DNMT3A, a de novo DNA methylation enzyme, are highly expressed in lower limb arteries of PAD patients and lowest expression is present in lower limb veins of PAD patients with critical ischemia." (PMID 31440517, 2019).
lentivirus infection (3 papers, 2015 to 2025). Virus diseases caused by the Lentivirus genus. "Consistently, we regulated reversely HDAC7 in DNMT3a overexpression or knockdown LUAD cells by lentivirus infection, HDAC7 overexpression or knockdown could partially reverse the DNMT3a-induced c-Myc proteins changes, which was confirmed by western blotting." (PMID 39990668, 2025). "The regulatory and functional roles of DNMT3a and TET2 were studied by lentivirus infection and puromycin selection." (PMID 38528605, 2024).
leukocytosis (3 papers, 2016 to 2023). "At 10 months post bone marrow transplantation, mice with the combined Kmt2a-PTD and DNMT3A-MT showed hepatosplenomegaly and leukocytosis with a shorter latency compared to control and DNMT3A-wild-type." (PMID 32015320, 2020).
lymph node metastasis (3 papers, 2012 to 2025). "DNMT1 expression was associated with age of the patients, menopause status, and tumor localization, while DNMT3a expression was associated with histological types and serum CA125 levels and DNMT3b expression was associated with lymph node metastasis." (PMID 22768205, 2012). "Furthermore, LUAD patients with deep tumour invasion and/or a large tumour size (T3/T4), a high American Joint Committee on Cancer (AJCC) 8th edition stage (stage III-IV) and lymph node metastasis (N1-N3) had higher expression of DNMT3a." (PMID 39990668, 2025). "Low expression of DNMT3A, low expression of DNMT3B, and locoregional lymph node metastases at presentation (N+-status) were significant significantly associated with disease-specific mortality in univariable Cox regression analysis (p = 0.029, p = 0.047, p = 0.001, respectively)." (PMID 40507223, 2025). "DNMT3a expression was positively associated with serum CA125 level, while DNMT3b expression was associated with lymph node metastasis and serum CA199 level, which is novel and was not report before." (PMID 22768205, 2012).
lymphoid neoplasm (3 papers, 2022 to 2025). A neoplasm composed of a lymphocytic cell population which is usually malignant (clonal) by molecular genetic and/or immunophenotypic analysis. "Previous case reports have demonstrated AITL following either a myeloid or lymphoid neoplasm derived from a common TET2/DNMT3A mutated stem cell population." (PMID 38199781, 2023). "Two unique cases show parallel evolution of distinct lymphoid neoplasms from a common TET2/DNMT3A mutated haematopoietic progenitor." (PMID 35064935, 2022). "We have encountered two unique cases in which a lymphoid neoplasm was identified and shown to share the TET2 and DNMT3A mutations seen in an underlying neoplastic TFH cell proliferation/smouldering AITL in each case." (PMID 35064935, 2022).
mastocytosis (3 papers, 2012 to 2025). A clonal myeloproliferative neoplasm characterized by the proliferation and accumulation of neoplastic mast cells in one or multiple organs or organ systems. "The identification of UPD2p in a patient with SM-AHNMD (CMML) indicated the occurrence of DNMT3A mutations in mastocytosis, which was confirmed by the detection of a homozygous mutation in this patient and two heterozygous mutations in other 2 patients with ISM." (PMID 22905207, 2012). "Furthermore, different mutations in DNMT3A (including the most prevalent one affecting amino acid R882, as well as frameshift, nonsense, and splice‐site mutations) are predicted to impact translation in patients with mastocytosis." (PMID 41031827, 2025). "Moreover, genes whose products influence epigenetic processes including TET2, DNMT3A or ASXL1 may be altered (mutated) in mastocytosis." (PMID 33803981, 2021). "In conclusion, TET2, DNMT3A and ASXL1 mutations are also present in mastocytosis and these mutations may affect prognosis, as demonstrated by worse OS in mutated patients." (PMID 22905207, 2012). "The identification of TET2, DNMT3A and ASXL1 mutations in mastocytosis suggest that these defects may alter the epigenetic machinery of the hematopoietic cells in myeloid malignancies, including mastocytosis." (PMID 22905207, 2012). "In the current article, we provide an overview of epigenetic changes that may occur and be relevant to mastocytosis, including mutations in genes involved in epigenetic processes, such as TET2, DNMT3A and ASXL1, and global and gene-specific methylation patterns in neoplastic cells." (PMID 33803981, 2021). "The results align with our previous findings, which determined TET2, DNMT3A, SETD2 and BRD4 genes as promising candidates for further analysis, warranting future study in a larger cohort of mastocytosis patients." (PMID 41031827, 2025).
medulloblastoma (3 papers, 2021 to 2024). A malignant, invasive embryonal neoplasm arising from the cerebellum. "For example, Mll4 deletion downregulates tumor suppressor genes (e.g., Bcl6 and Dnmt3a) by generally decreasing the abundance of SEs and H3K4me3 and causing widespread degradation of these epigenomic marks during medulloblastoma generation." (PMID 37501079, 2023). "As similar mechanism of action, loss of function of KMT2D inhibits tumor suppressor genes DNMT3A and BCL6, upregulates NOTCH pathway, and induces medulloblastoma in murine models." (PMID 39113693, 2024). "Mll4 deletion downregulated tumor suppressor genes (Bcl6 and Dnmt3a) in medulloblastoma by decreasing SE function." (PMID 37501079, 2023). "Mechanistically, KMT2D upregulates expression of the tumor suppressor gene Dnmt3a whose protein, DNMT3A, downregulates expression of several oncogenic Ras activators to suppress medulloblastoma." (PMID 34194626, 2021). "We have shown that KMT2D-activated tumor-suppressive super-enhancers interact with the promoters of the DNA methyltransferase gene Dnmt3a and the medulloblastoma suppressor gene Bcl6 and upregulate these genes to suppress medulloblastoma genesis." (PMID 34194626, 2021).
memory impairment (3 papers, 2019 to 2024). "Knockdown of DNMT3a leads to synaptic disorder and memory impairment in aged mice." (PMID 39722450, 2024).
metastatic melanoma (3 papers, 2012 to 2023). A melanoma that has spread from its primary site to another anatomic site. "We observed that both METTL4 and DNMT3A were significantly upregulated in metastatic melanoma samples as compared to primary tissue." (PMID 31217906, 2019). "Besides that, the up-regulation of Dnmt3a protein was only found for 4C11+ metastatic melanoma cell line." (PMID 22984562, 2012).
metastatic tumor (3 papers, 2019 to 2023). "Three new somatic mutations, including ERBB3, DNMT3A and NOTCH1 mutations were detected in the metastatic tumor." (PMID 30850667, 2019). "DNMT3A levels increased from non-neoplastic to tumor tissue at both the mRNA and protein level and further increased with increasing the grade of the tumors, although their levels were lower in higher stages and in metastatic tumors." (PMID 37894317, 2023).
ovarian tumors (3 papers, 2012 to 2023). "In the present study, we for the first time immunohistochemically determined the expression of DNMT1, DNMT3a, and DNMT3b proteins in benign and malignant ovarian tumor tissues." (PMID 22768205, 2012). "MiR-29a was under-expressed and DNMT3A mRNA was over-expressed in the DNA methylation subtype “MC2”; furthermore, possible targets of DNMT3A methylation in the ovarian tumors (having DNA methylation levels correlated with DNMT3A expression) were enriched for genes showing an impact by methylation." (PMID 22479643, 2012).
peripheral nerve injury (3 papers, 2017 to 2023). Injury to a peripheral nerve. "In support of this hypothesis, DNMT3a levels are upregulated and DNMT3a accessibility to uniquely hypomethylated gene loci is increased in affected DRG for days in peripheral nerve injury models." (PMID 33323031, 2021). "Dnmt3a, an epigenetic repressor, participates in epigenetic silencing of several genes (such as Oprk1 and Kcna2 besides Oprm1) in the injured DRG following peripheral nerve injury." (PMID 29170626, 2017). "DNMT1, with an established role in canonical methylation activity but also with recognized de novo methylation actions, and DNMT3a, through repression of Kcna2, were found upregulated in the DRG after peripheral nerve injury in mice, and their inhibition or knockout diminished pain hypersensitivity." (PMID 37108466, 2023).
preeclampsia (3 papers, 2018 to 2022). Preeclampsia is a hypertensive disorder of pregnancy that is characterized by new-onset hypertension with proteinuria presenting after 20 weeks of gestation, and depending on mild or severe forms may initially present with severe headache, visual disturbances, and hyperreflexia. "While this likely has global implications for the DNA methylation pattern observed in these cluster 3 placentas, decreased expression of DNMT3A has been specifically implicated in immunological-associated disorders and abnormal placentation in preeclampsia." (PMID 29507646, 2018). "For example, downregulation of DNA methyltransferase 3A (DNMT3A) results in increased IGFBP5 in patients with preeclampsia due to hypomethylation of the IGFBP5 promoter." (PMID 36465383, 2022). "Therefore, we suggest the regulation of global methylation via DNMT1 and DNMT3A and their dysregulation in preeclampsia under lower folate levels." (PMID 35578613, 2022).
Rett syndrome (3 papers, 2020 to 2022). A severe neurodevelopmental disorder affecting the central nervous system. "DNMT3A haploinsufficiency in mice causes behavioral abnormalities and epigenomic dysregulation that overlap with Rett syndrome and ASD." (PMID 35646933, 2022).
sarcoma (3 papers, 2022 to 2025). A usually aggressive malignant neoplasm of the soft tissue or bone. "In synovial sarcoma, the mRNA expression levels of DNMT1 and DNMT3B were similar to or lower than those in other sarcomas, whereas DNMT3A exhibited higher expression levels." (PMID 40299558, 2025). "RB1, a gene classified as a driver in sarcoma by COSMIC, is also well connected in our solution, linking protein kinase C inhibitor staurosporine to the seed genes MYC, SKP2 and DNMT3A." (PMID 35580047, 2022).
Splenomegaly (3 papers, 2016 to 2020). Abnormal increased size of the spleen. "Upon euthanasia, the Dnmt3a+/−;D61Y mice showed obvious splenomegaly and the spleen to body weight percentage was significantly increased compared to the other three genotypes." (PMID 29464054, 2018). "In addition to splenomegaly, the double mutant mice also showed significantly higher peripheral blood WBC counts compared to WT or Dnmt3a+/− mice." (PMID 29464054, 2018).
steatosis (3 papers, 2020 to 2023). Increased lipid within the cytoplasm of cells. "We, thus, examined whether the occupancy of SHP and DNMT3A and DNA methylation at lipogenic genes are altered in NAFLD patients with steatosis or NASH-fibrosis." (PMID 33235221, 2020).
acute kidney injury (2 papers, 2023 to 2024). Sudden and sustained deterioration of the kidney function characterized by decreased glomerular filtration rate, increased serum creatinine or oliguria. "Epigenetic alterations are related to acute kidney injury-to-chronic kidney disease transition, and the roles of DNMT3A, TET2, and ASXL-1 in kidneys are reported." (PMID 37928907, 2023). "Although DNMT3A and DNMT3B knock-out mice displayed no obvious kidney abnormalities, they showed resistance to acute kidney injury (AKI)." (PMID 37928907, 2023).
adenoma (2 papers, 2013 to 2016). A neoplasm arising from the epithelium. "CD80 mRNA levels were inversely correlated with the DNMT3A mRNA levels in healthy colonic mucosa of patients with adenoma and with DNMT3B in healthy colonic mucosa of patients with cancer (τ = −0.44, p = 0.07 and τ = −0.50, p = 0.04, respectively)." (PMID 27377375, 2016).
aortic valve stenosis (2 papers, 2021 to 2023). Aortic valve stenosis (AVS) is a condition characterized by narrowing of the heart's aortic valve opening. "Mutations in the clonal hematopoiesis of indeterminate potential (CHIP)-driver genes DNMT3A and TET2 have been previously shown to be associated with short-term prognosis in patients undergoing TAVR for aortic valve stenosis." (PMID 36680616, 2023). "DNMT3A- and TET2-CHIP-driver mutations are associated with long-term mortality in patients with aortic valve stenosis even after a successful TAVR." (PMID 36680616, 2023).
biliary atresia (2 papers, 2018 to 2019). A rare, biliary tract disease characterized by progressive obliterative cholangiopathy of the intra- and extrahepatic bile ducts, occurring in the embryonic/ perinatal period, leading to severe and persistent neonatal jaundice and acholic stool. "We found the overexpression of miR-142-5p and mRNA level of DNA methyltransferase (DNMT) 1, and miR-29b and DNMT3a/DNMT3b were significantly negatively correlated in biliary atresia livers." (PMID 29748604, 2018). "Our study showed that DNMT1, DNMT3a, and DNMT3b expression is significantly decreased, while the expression level of IFN-γ is increased in liver samples of biliary atresia cases." (PMID 29748604, 2018).
bone cancer (2 papers, 2025). A primary or metastatic malignant neoplasm affecting the bone or articular cartilage. "Firstly, other studies suggested that DNA demethylases and methylases like DNA methyltransferase 3 alpha, which silences Kv1.2 in the spinal dorsal horn, contribute to pain development, including bone cancer pain." (PMID 39864621, 2025).
Burkitt lymphoma (2 papers, 2017 to 2022). A rare form of malignant mature B-cell non-Hodgkin lymphoma. "Based on our expression profiling, we conclude that DNMT1 and DNMT3B are consistently overexpressed in MYC-driven T-ALL and Burkitt’s lymphoma cell lines, while DNMT3A is overexpressed in human T-ALL cell lines only." (PMID 29100357, 2017). "Similarly, high expression of DNMT3B and DNMT3A suppressed expression of miR-29 through methylation modification and induced disease progression in Burkitt lymphoma." (PMID 35129056, 2022). "Burkitt’s lymphoma did not display increased DNMT3A levels, implicating a differential mechanism of regulation." (PMID 29100357, 2017). "In contrast, DNMT3A mRNA levels were not much higher in Burkitt’s lymphoma (1.09-fold, P=0.031) than in normal B-cells, which is consistent with our cell line analysis." (PMID 29100357, 2017). "To determine whether DNMT1 and DNMT3B transcription in T-ALL and Burkitt’s lymphoma-like cells is directly regulated by oncogenic MYC, we performed chromatin immunoprecipitation (ChIP) analysis measuring MYC binding to the genomic loci of DNMT1, DNMT3A and DNMT3B." (PMID 29100357, 2017). "To unravel the role of DNA methyltransferases (DNMTs) in MYC-driven hematopoietic malignancies, we performed expression profiling for DNMT1, DNMT3A and DNMT3B comparing MYC-driven T-ALL and Burkitt’s lymphoma cells to non-malignant control cells." (PMID 29100357, 2017). "In contrast, DNMT3A mRNA was increased in all human T-ALL (49.35- and 61.88-fold, P<0.001), but not in all Burkitt’s lymphoma cell lines." (PMID 29100357, 2017).
cardiomyopathy (2 papers, 2024 to 2025). A disease of the heart muscle or myocardium proper. "Kyoto Encyclopedia of Genes and Genomes (KEGG) pathway analysis showed that Dnmt3a-Tg muscle is enriched in pathways associated with cardiomyopathy." (PMID 40151644, 2025).
chronic kidney disease (2 papers, 2023). Impairment of the renal function secondary to chronic kidney damage persisting for three or more months. "In any case, no studies have been carried out on model animals deficient in TET2 or DNMT3a with chronic kidney disease in order to discern whether the mutations of each gene separately have a different effect on the atherogenic risk in this population." (PMID 37763205, 2023).
cylindroma (2 papers, 2019). "For example, statistical analyses revealed significant enrichment of mutations in DNMT3A in cylindromas, a gene previously linked to hematopoietic malignancies, where it plays a role in the regulation of DNA methylation." (PMID 31101826, 2019). "CYLD and DNMT3A were identified as statistically significant driver genes in cylindroma." (PMID 31101826, 2019). "To investigate whether DNMT3A mutational heterogeneity correlated with CCS tumor histophenotypes, we studied five tumors that contained intratumoral cylindroma and spiradenoma." (PMID 31624251, 2019). "DNMT3A protein expression was also increased in CCS tumors compared to control skin and hair, and regions of heterogeneity were observed between islands of cylindroma." (PMID 31624251, 2019).
dysplasia (2 papers, 2025). A usually neoplastic transformation of the cell, associated with altered architectural tissue patterns. "DNMT3a expression could be detected in all dysplasia grades including dysplasia-free vulvar tissue." (PMID 40022051, 2025). "CHIP is currently defined by the presence of somatic mutations commonly seen in hematologic malignancies (e.g., DNMT3A, TET2, ASXL1) in individuals without cytopenia or dysplasia." (PMID 41464583, 2025).
gallbladder cancer (2 papers, 2024 to 2025). "Interestingly, DNMT3A recruited by YAP/TAZ guides DNA methylation to drive gallbladder cancer metastasis, and YAP signaling contributes to DNA methylation remodeling upon mouse embryonic stem cell differentiation." (PMID 40739083, 2025). "Interestingly, DNMT3A recruited by YAP/TAZ guides DNA methylation to drive gallbladder cancer metastasis, and YAP signaling also contributes to DNA methylation remodeling upon mouse embryonic stem cell differentiation." (PMID 40739083, 2025).
growth disorder (2 papers, 2019 to 2020). "Germline mutations in fundamental epigenetic regulatory molecules including DNA methyltransferase 3 alpha (DNMT3A) are commonly associated with growth disorders, whereas somatic mutations are often associated with malignancy." (PMID 31160375, 2019).
Hypercholesterolemia (2 papers, 2024 to 2025). An increased concentration of cholesterol in the blood. "DNMT3A mutation was a significant predictor for ATE (OR 5.4, 95% CI 1.30-22.42, p = 0.02) after adjusting for sex, age, and cardiovascular risk factors: smoking, arterial hypertension diabetes mellitus hypercholesterolemia, in the multivariable analysis." (PMID 40287867, 2025).